CD40 (CD40 molecule)
Diseases named in the same sentence as CD40 in open-access papers (continued):
Sharing a sentence is not in itself a finding about the gene and the disease.
autoimmune disease (continued). "Consistent with opposing roles of BCR and CD40 signaling, previous work has suggested that variants that disrupted the signaling of either BCR and CD40 caused an imbalance of positive and negative selection and lead to immunodeficiency or autoimmune diseases." (PMID 40473841, 2025). "Therefore, CD40/CD40L inhibitors have the potential to treat autoimmune disorders by inhibiting the CD40 signaling pathway and inactivating immune cells." (PMID 37889398, 2023). "In addition, according to a genome-wide association study, autoimmune disease (e.g., SLE and rheumatoid arthritis) and MCLS share common candidate genes (e.g., BLK and CD40)." (PMID 38125818, 2023). "Similarly, CD40 and its interaction with CD40L, are implicated in the pathogenesis of autoimmune diseases, particularly in SLE nephritis." (PMID 35693781, 2022). "Since CD40 has been shown to play a role in a number of autoimmune diseases including GD, Iscalimab has begun preliminary testing in several autoimmune conditions including myasthenia gravis, rheumatoid arthritis, Sjogren’s syndrome, and systemic lupus erythematosus (SLE)." (PMID 34149627, 2021). "If so, sCD40L at levels in autoimmune disease patients may sufficiently trigger integrin activation and subsequent CD40/CD40L signaling for inflammatory responses." (PMID 33571526, 2021). "Moreover, IL-21 not only induces the differentiation of B cells into plasma cells, but also promotes the proliferation of germinal center B cells and antibody production through CD40L/CD40 interaction, thus participating in autoimmune disorders." (PMID 34669781, 2021). "A previous study from our group suggested that the observed sleep–wake dysregulations in autoimmune diseases may result from CD40-induced TNF-TNFR1 mediated alterations of molecular pathways, which regulate the sleep–wake behavior." (PMID 34440067, 2021). "The CD40 immune-activation pathway has been found to play a pivotal role in the host response to infectious pathogens and in the pathogenesis of autoimmune diseases including autoimmune hepatitis, primary biliary cirrhosis, inflammatory bowel disease, rheumatoid arthritis, and multiple sclerosis." (PMID 34440067, 2021). "All of these findings suggest that CD40 could be a potential target for drug development for the treatment of autoimmune diseases." (PMID 33371207, 2020). "CD40L/CD40 interactions have been found to be important in autoimmune diseases such as SLE." (PMID 33292359, 2020). "Despite all efforts, there is a possibility that a general, systemic CD40(L) blockade, while being suitable for the short-term treatment of exacerbations in autoimmune diseases, has limiting side effects in the long-term treatment of patients with cardiovascular disease." (PMID 33198327, 2020). "Anti-CD40 mAbs that either potentiate or inhibit this pathway therefore possess powerful immune effects and are being explored in clinical trials to treat cancer and autoimmune diseases, respectively." (PMID 32442402, 2020). "In addition to B cell depletion, antibodies with CD40 agonist activity produce increases in liver enzymes and cytokine release that present safety concerns in patients with autoimmune disease." (PMID 31382872, 2019). "Moreover, recent studies have shown widespread expression of CD40 for inflammatory liver diseases, including allograft rejection, autoimmune disease, and viral hepatitis." (PMID 30662889, 2018). "CD40 plays an important role in the development and progression of various autoimmune diseases." (PMID 28133421, 2017). "Interestingly, high levels of CD40 and CD40L or engagement of CD40/CD40L are also associated with the same sets of autoimmune diseases such as SLE and Aicardi-Goutieres syndrome (AGS)." (PMID 27716849, 2016). "Our data suggest an alternative mechanism that CD40 may contribute to autoimmune diseases through elevated activities of STING and IFN-I production." (PMID 27716849, 2016).
autoimmune disease (continued). "Further research is needed to better elucidate how the CD40 axis may help control other autoimmune diseases." (PMID 27818660, 2016). "Our observation of CD40 enhancement of STING mediated IFN-I production provides an alternative mechanism that may unite these two hallmarks of autoimmune diseases." (PMID 27716849, 2016). "Thus, the CD40 signaling pathway is considered to be a promising target for the clinical treatment of autoimmune diseases." (PMID 26809818, 2016). "Therefore, the increase in CD40 expression and the subsequent exaggerated CD40/CD40L interactions potentially lead to the development of autoimmune diseases." (PMID 26528290, 2015). "CD40 signaling is critical for Breg cell generation and function in autoimmune disorders." (PMID 24887143, 2014). "The role of the CD40L in the susceptibility to autoimmune diseases has not been investigated as broadly as the CD40, mainly due to this gene being located on the × chromosome." (PMID 23166616, 2012). "Interaction between CD40L and CD40 plays a central role in the activation of the immune system, such as immunoglobulin G (IgG) switching, autoimmune disease, antiviral effect, allograft rejection, cytokines regulation, arthrosclerosis, and endothelial cell interaction." (PMID 22645426, 2012). "The role of the CD40LG in the susceptibility to autoimmune diseases has not been investigated as broadly as that of CD40, mainly because this gene is located on the × chromosome." (PMID 22731751, 2012). "Our finding of the increase in CD40-expressing DCs in lupus-prone mice before the onset of the disease suggests that CD40 on DCs may have a role in the pathogenesis of this autoimmune disease." (PMID 16507174, 2006). "Hence, when administering patients with CD40-blockade therapy for treating autoimmune diseases, whether it will be accompanied by higher risks of developing AD and AA?" (PMID 36437950, 2022). "Taken together, our results suggest that Tespa1 may be a previously unsuspected missing component of the CD40-proximal signaling machinery in B cells, placing Tespa1 in a key position to regulate B cell-mediated autoimmune diseases and suggests possible new signaling pathways in B-lymphocytes." (PMID 29867947, 2018). "Defining the genotype-independent but disease-dependent changes in B lymphocyte and dendritic cell CD40 levels identified in this study could uncover protective roles for CD40 in MS that fundamentally distinguish its pathogenesis from that of other autoimmune diseases." (PMID 26068105, 2015). "Multiple candidate gene studies have also identified and validated the association of SNPs in CD40 with several autoimmune diseases including Graves’ disease, rheumatoid arthritis, and multiple sclerosis but there were no study on CD40 gene polymorphisms and outcome of transplantation." (PMID 25426283, 2014). "Although CD40 might be a common susceptibility locus for some autoimmune diseases, our results do not suggest an important role of CD40 in the susceptibility to SSc." (PMID 22731751, 2012). "Associations between CD40 polymorphisms have mainly been shown in autoimmune diseases and the absence of an association with FUS may be due to its infectious etiology." (PMID 21976957, 2011). "Moreover, the rs1883832 CC genotype which could enhance CD40 translational efficiency has been shown to induce the development of autoimmune diseases, such as Grave's disease." (PMID 21912605, 2011). "Reduced expression of CD40 and CD86 can alleviate diseases such as chronic inflammatory disease and autoimmune disease because they are crucial for productive interactions between T cells and APCs cells." (PMID 38015971, 2023). "Since CD40/CD40L are essential components in both innate and acquired immunity, monoclonal antibodies targeting CD40/CD40L, either antagonistic or agonistic, have attracted widespread attention in the field of autoimmune diseases and cancers, respectively." (PMID 36437950, 2022).
autoimmune disease (continued). "CD40 interacts with its ligand, CD40L (CD154), and plays a prominent role in many autoimmune diseases, such as rheumatoid arthritis (RA), multiple sclerosis (MS), and systemic lupus erythematosus (SLE)." (PMID 34867801, 2021). "As cited above, in addition to CD40, defective regulation of engagement or signalling through other co-stimulatory receptors such as CD5, CD22 and FcγRIIB can also promote autoimmune diseases." (PMID 28456914, 2017). "After T cell activation, the expression of CD40/CD40L increases on the cell surface, leading to a variety of autoimmune diseases, including GD." (PMID 28133421, 2017). "The expression of co-stimulatory molecules, such as CD40 and CD80, is enhanced on B cells in autoimmune diseases such as SLE and is involved in the interactive activation with surrounding immunocompetent cells including autoreactive T cells." (PMID 29259679, 2016). "Given its central role as a key regulator and amplifier of immune reactivity, the CD40/CD40 ligand (CD40L) system significantly contributes to the development and progression of multiple autoimmune diseases, including IBD." (PMID 26528290, 2015). "There can be potential benefit in the blockade of the interaction between CD40 and CD40L in the therapy of autoimmune diseases or the suppression of the allograft rejection." (PMID 19865524, 2009). "In addition, another novel gene, IL2RA interacts with the well-known autoimmune disease genes CCR6, IRF5, and CD40, which are the hub genes in the network." (PMID 38360850, 2024). "The CD154/CD40 pathway also plays a crucial role in the development of EAE, and disrupting this communication by blocking antibodies had beneficial effects not only in EAE but also in other autoimmune disease models." (PMID 34831335, 2021). "Iscalimab is a nondepleting human anti-CD40 monoclonal antibody that is currently under clinical investigation in several autoimmune diseases, including RA and GD." (PMID 34484118, 2021). "Dysregulation of B cells and autoAb production in SLE-like autoimmune disease are influenced by both innate (TLR) and adaptive (CD40) pathways and Tfh secreted IL-21 which regulates B cell differentiation into plasma cells, memory B cells and CD11chi ABC B cells." (PMID 34512628, 2021). "Essentially, the ability to skew the adaptive immune response towards a Th1 phenotype and retain low frequencies of Treg cells through CD40 expression and co-stimulation represents a novel mechanism in which latent γ-herpesviruses like EBV can act to facilitate and induce autoimmune disease." (PMID 26356194, 2015). "CD40 engagement in both T or B cells leads to the production of cytokines, such as IL-12, IL-2, TNF-α, IFN-α, and CD80, developing an environment which is conducive to autoimmune diseases." (PMID 23533546, 2013). "Further, and besides the involvement of platelets in several diseases the presented markers, such as CD40, in autoimmune diseases such as inflammatory bowel disease, multiple sclerosis, psoriasis, or other autoimmune diseases, we had no patients with these diseases." (PMID 36830917, 2023). "The interaction of the cell surface receptor CD40 and its ligand CD40L (CD154) is known to play a central role in the regulation of humoral and cellular immunity and in the pathogenesis of these autoimmune diseases; thus, targeting this interaction may be a therapeutic option." (PMID 29127458, 2018). "CD40 expression on non-hematopoietic cells can also engage CD40L, leading to a pro-inflammatory response, being extensively studied in autoimmune diseases." (PMID 38742115, 2024). "Upregulated expression of CD40 and CD154 occurs in immune effector cells and non-immune cells in different autoimmune diseases." (PMID 31426619, 2019). "In humans, iscalimab, a fully human, non-depleting anti-CD40 antibody, showed its safety and capability to inhibit humoral response to vaccination and to inhibit CD154-induced B cell activation, supporting its potential interest in autoimmune diseases." (PMID 33801294, 2021).
melanoma (112 papers, 2006 to 2026). A malignant, usually aggressive tumor composed of atypical, neoplastic melanocytes. "Consistently, RAS (N/H/K) mutation alone (p = 0.058), or in combination with NF1 mutation (p = 0.038), was associated with a reduced CD40 expression in TCGA-melanoma (Firehose Legacy database, n = 479)." (PMID 34758832, 2021). "An extensive search of human cancer databases indicates that the gain of CD40/CD80/ICOSL copy number in melanoma patients is associated with significantly better survival." (PMID 34092233, 2021). "Previous studies show that CD40 stimulation activates tumor-associated Mφs or T cells and inhibits tumor progression in melanoma, lymphoma, and pancreatic carcinoma." (PMID 34103524, 2021). "Expression of CD40 by melanoma cells is associated with therapeutic response to RAF/MEK inhibition and ICB." (PMID 34092233, 2021). "Combining agonistic CD40 mAb therapy with the IDO1 inhibitor epacadostat delayed tumor growth in B16-F10 melanoma, associated with increased activation of tumor-infiltrating T-cells." (PMID 32231867, 2020). "Here we have identified changes in endothelial gene expression associated with agonistic CD40 mAb immunotherapy through isolation of tumor endothelial cells from B16-F10 melanoma followed by RNA-sequencing." (PMID 32231867, 2020). "CD40-activated B cells pulsed with melanoma cell lysates potently stimulate peripheral autologous T cells specific to melanoma-associated antigens." (PMID 26883106, 2016). "Anti-CTLA-4 mAb and anti-CD40 mAb administered with liposome-encapsulated peptide vaccine or an adenoviral vector encoding melanoma antigen induced effective tumor-specific CD8+ T cells with no detrimental side effects." (PMID 27827885, 2016). "Vaccination with recombinant adenovirus encoding melanoma antigen delayed tumor growth in 30%–40% of mice, while vaccination in combination with anti-CD40 and anti-CTLA-4 mAbs induced complete response." (PMID 27827885, 2016). "Moreover, expression of the co-stimulatory receptor CD40 is associated with enhanced responsiveness of melanoma to immune checkpoint blockade therapy." (PMID 37868988, 2023). "Notably, high CD40 is associated with better overall survival (OS) in two melanoma cohorts of patients treated with α-CTLA4 (n = 15, p = 0.0067) or α-PD1 (n = 47, p = 0.0381)." (PMID 34758832, 2021). "RAS (N/H/K) mutation correlates with low CD40 expression in melanoma." (PMID 34758832, 2021). "Notably, the RGS induced CD40 upregulation on melanoma cells, which is associated with cell death and tumor antigen release, indicating that CD40 was required for the induction of anti-tumor immune responses." (PMID 34092233, 2021). "Here we have linked response to RGS to expression of CD40 by melanoma tumor cells." (PMID 34092233, 2021). "Similarly, an antigen-specific T cell response (IFNγ and lytic enzymes secretion) was induced following stimulation with a melanoma-associated antigen recognized by T cells (MART-1: melanoma antigen recognized by T cells 1) mRNA-loaded CD40-activated B cells." (PMID 34576154, 2021). "However, we observed heterogeneity of CD40 expression among the melanoma tissues bearing oncogenic NRAS and BRAF mutations." (PMID 34758832, 2021). "Together, our data indicate that IDO1 is mainly expressed in tumor endothelial cells of B16-F10 and HCmel12 melanomas and that its expression can be further enhanced by agonistic CD40 mAb therapy and the associated IFNγ expression in the tumor microenvironment." (PMID 32231867, 2020). "In melanoma, CD40 activation enhances dendritic cell (DC) maturation and cross-presentation of tumor antigens, leading to robust CD8+ T cell–mediated cytotoxicity." (PMID 40821795, 2025). "Specifically, PD-L1 (CD274) mRNA was detected in melanoma cells, along with CD40 and B7-H3 (CD276) mRNAs." (PMID 40647495, 2025).
melanoma (continued). "Nevertheless, a phase II trial evaluating nivolumab combined with the CD40 agonist sotigalimab in patients with melanoma resistant to prior immune checkpoint inhibitors demonstrated a modest 15% overall response rate." (PMID 41182434, 2025). "First, we found that subcutaneous tumors from TC-1 (lung adenocarcinoma) and B16 (melanoma) cancer cells were responsive to combined anti-CD40/anti-PD-1 immunotherapy in WT mice but resisted treatment in Keap1flox/flox VavCre mice." (PMID 41176316, 2025). "A phase II trial demonstrated that the CD40 agonist sotigalimab combined with nivolumab induced durable responses in PD-1 inhibitor-resistant melanoma patients, achieving an ORR of 15.2% (5/33 partial responses) with a median duration of response ≥26 months." (PMID 40933890, 2025). "We previously reported that IL-1 pathway blockade enhances agonistic CD40 antibody efficacy against melanoma by depleting polymorphonuclear myeloid-derived suppressor cells (PMN-MDSCs; CD11b+Ly6C+Ly6G+)." (PMID 40060615, 2025). "The vaccine formula components included three TLR ligands (LTA, Poly I:C, and Resiquimod) and an anti-CD40 antibody, which were tested in melanoma and triple-negative breast cancer (TNBC) models." (PMID 39941108, 2025). "For instance, MDSCs induce reprogramming of TAMs by suppressing CD40/IL-27 signals to promote melanoma progression in systemic lupus erythematosus mice." (PMID 40453088, 2025). "Beyond antigen-presenting cells, CD40 is found on various human cancer cell types, including carcinomas, melanomas, and B cell lymphomas." (PMID 40397730, 2025). "It has been reported that CD40 levels are high in cancer types such as malignant melanoma, lung cancer, and stomach cancer." (PMID 39625893, 2024). "Here, we investigated the antimelanoma activity of combination therapy using NU7441 (NU) and the immune adjuvants STING ligand plus the CD40 antibody agonist (NU-SL40) in mice bearing immunoresistant B16-F10 melanoma tumors." (PMID 39436696, 2024). "Upregulations of Cxcl9, Cxcl10, Cxcl11, Ccl5, Tap1, CD74, Irf1, Icam1, CD40, Fas and PD-L1 were detected after Mi-2β silencing and the anti-PD-1 treatment in BRafV600E/Ptennull melanomas." (PMID 38461299, 2024). "In human trials, chemotherapy combined with agonistic anti-CD40 has shown promising anti-tumor immune response in solid tumors such as melanoma, mesothelioma, and pancreatic cancer." (PMID 39178856, 2024). "The distribution of CD3+ T cells and CD40 expression was evaluated from nine melanoma patients with stage III disease and one stage II disease." (PMID 37509357, 2023). "It has also been reported that high CD40 expression in melanomas is correlated with antitumor immune responses, better prognosis, and positive response to immune checkpoint blocking therapy or targeted therapy." (PMID 37970926, 2023). "From these data, two melanoma tumors were selected for study in the humanized model based on CD40 and CD3 staining." (PMID 37509357, 2023). "In biopsies of melanoma and other epithelial tumors, CD40 expression is found in over 60% of the samples." (PMID 37970926, 2023). "The combination therapy of agonistic anti-CD40 monoclonal antibody and CSF-1R inhibitor effectively inhibits tumor growth in mouse models of melanoma by targeting TAMs, transforming “cold” into “inflamed” tumor microenvironment." (PMID 35585567, 2022). "Mechanistically, rigosertib upregulated CD40 expression on melanoma cells, promoted immunogenic cell death, and increased DC enrichment and T-cell responses in the tumor microenvironment." (PMID 35806358, 2022). "APX005M and SEA-CD40 are both humanized IgG1 agonistic CD40 mAbs currently tested in melanoma in multiple phase 2 trials, in combination with pembrolizumab (NCT02706353, NCT04337931, NCT04993677)." (PMID 36211808, 2022). "Accordingly, a CD40 agonist combined with TLR agonists significantly increases T-cell responses to peptide-based vaccinations in murine melanoma models." (PMID 35062731, 2022).